EMX1 (empty spiracles homeobox 1)
Description:
Transcription factor, which in cooperation with EMX2, acts to generate the boundary between the roof and archipallium in the developing brain. May function in combinations with OTX1/2 to specify cell fates in the developing central nervous system.
Tractability: PROTAC: its protein half-life has been measured.
Gene: Protein-coding gene on chromosome 2 (72,916,260 to 72,936,071, forward strand). Ensembl gene ENSG00000135638.
Subcellular location: Nucleus; Cytoplasm
Subcellular location (Human Protein Atlas): Nucleoli; Nucleoli rim; Mitotic chromosome
Gene Ontology:
Molecular function: protein binding; sequence-specific double-stranded DNA binding; DNA-binding transcription factor activity, RNA polymerase II-specific; RNA polymerase II cis-regulatory region sequence-specific DNA binding; DNA binding
Biological process: brain development; central nervous system development; neuron differentiation; regulation of transcription by RNA polymerase II; regulation of DNA-templated transcription
Cellular component: nucleolus; nucleus; chromatin; cytoplasm
Genetic constraint (gnomAD): Loss-of-function variants: 10 observed, 12.8 expected, observed/expected ratio (o/e) 0.78, 90% interval 0.48 to 1.32. The synonymous counts are far from expectation, so gnomAD's model fits this gene poorly and the ratio says little. Missense variants: 424 observed, 322.32 expected, observed/expected ratio (o/e) 1.32, 90% interval 1.21 to 1.43. Synonymous variants: 250 observed, 153.81 expected, observed/expected ratio (o/e) 1.63, 90% interval 1.47 to 1.8.
Homologues: Orthologues: macaque EMX1 (99% identical), chimpanzee EMX1 (99% identical), dog EMX1 (97% identical), pig EMX1 (97% identical), rat Emx1 (92% identical), guinea pig EMX1 (88% identical), mouse Emx1 (85% identical), rabbit EMX1 (70% identical), zebrafish emx1 (59% identical), tropical clawed frog emx1 (53% identical). Paralogues in human: EMX2 (58% identical), VAX1 (21% identical), VAX2 (20% identical).
Diseases named in the same sentence as EMX1 in open-access papers:
EMX1 is named in the same sentence as 64 diseases in open-access papers, as found by Europe PMC text mining. Sharing a sentence is not in itself a finding about the gene and the disease. The quoted sentences say what the papers report.
Anxiety (23 papers, 2014 to 2026). Intense feelings of nervousness, tension, or panic often arise in response to interpersonal stresses. "This argues against a contribution of the Cre driver line (via Emx1 heterozygosity or linked-polymorphisms) in the decreased anxiety observed in the cortical rescue mice." (PMID 25759645, 2015). "Finally, mice with loss of both BMPRIA and BMPRIB in the forebrain using the Emx1 promoter also showed reduced anxiety in the elevated plus maze and defects in fear conditioning." (PMID 26444546, 2015). "Our mouse model, using an Emx1-Cre to ablate Miro1, displays distinct anxiety-like behavior patterns that are distinct from those observed in previous models such as when Miro1 is removed using the Eno2-Cre." (PMID 41386992, 2026). "Thirdly, in the elevated plus maze (EPM) test, while the total distance traveled and time spent in open arms were unchanged, Emx1-Cre;Klf7F/F mice showed significantly fewer entries into the open arms, indicating increased anxiety." (PMID 40762575, 2025). "Firstly, open field tests revealed that Emx1-Cre;Klf7F/F mice displayed reduced exploratory behavior and heightened anxiety, as evidenced by their reluctance to explore the center regions of open fields and increased latency to enter the center zone." (PMID 40762575, 2025). "Our behavioral analyses revealed that Emx1-Cre; Klf7F/F mutant mice exhibit depressive- and anxiety-like behaviors, as well as memory impairments, underscoring the role of Klf7 in hippocampal function." (PMID 40762575, 2025). "Firstly, BDNF re-expression in the amygdala of Bdnflox/lox;Emx1-cre mutant mice reversed the previously observed alterations in anxiety-related behavior and metabolic function." (PMID 38672441, 2024). "When tested in the elevated plus maze, St8sia2−/− mice in cohort 2 showed signs of reduced anxiety that were fully reproduced by Foxb1-Cre;St8sia2f/f and, for the time spent in the closed relative to the open arm, also by Foxb1-Cre;Emx1-Cre;St8sia2f/f mice." (PMID 35115485, 2022). "Adult Emx1-Scrib−/− cKO and their control littermates (10–20 weeks) were submitted to tests for anxiety-, locomotor and exploratory activities." (PMID 33907211, 2021). "We previously reported hyperactivity and reduced anxiety in the Emx1-Rictor CKO mice in which neural progenitor cells (including oligodendrocyte and astrocyte precursors), were targeted." (PMID 29161318, 2017). "Mice doubly mutant for BMPRIA and BMPRIB in the forebrain produced using EMX1-(IRES)-Cre show reduced anxiety-like behavior." (PMID 26444546, 2015). "Next, anxiety behavior in adult cortical rescue (Htr1acR/cR; Emx1Cre/+) and control (Htr1acR/cR; Emx1+/+) mice was measured." (PMID 25759645, 2015). "The results indicated that CaMKIIα-Cre-dependent IRSp53 deletion in mice led to various behavioral deficits, including open-field hyperactivity, anxiety-like behaviors, and impaired social interaction, similar to the behavioral deficits induced by Emx1-Cre-dependent IRSp53 deletion." (PMID 35982261, 2022). "In addition, mice expressing Cre alone (Emx1-Cre and Viaat-Cre) showed normal social interaction, locomotion, or anxiety-like behavior." (PMID 32116566, 2020). "In anxiety-related behavioral tests, Emx1-Cre;Shank3Δ14–16 mice spent a normal amount of time in the center region of the open-field arena, but spent an increased amount of time in the open arm of the elevated plus-maze (EPM), and a normal amount of time in the light chamber of the LD apparatus." (PMID 31649512, 2019). "Noteworthy since a portion of neurons in the amygdala are generated from Emx1-expressing progenitors in the dorsal telencephalon, these neurons may also contribute to the decreased levels of anxiety-related behavior." (PMID 31213987, 2019).
Anxiety (continued). "Consistent with the observations in Nestin-Cre Utx cKO mice, these Emx1-Cre Utx cKO mice also displayed anxiety-like behaviors as indicated by decreased entry into the center zone in the open field test, decreased entries, and time spent in the light box in the light-dark box test." (PMID 28970783, 2017). "Despite earlier reports to the contrary, we did not see any alterations in anxiety behavior associated with the Emx1-Cre allele on the knockout background." (PMID 25759645, 2015). "Indeed, mice with deficiencies in certain neural identity markers, like cortical marker EMX1, demonstrate lower levels of depressive behaviors, denoted by reduced immobility time in the forced swim test and reduced anxiety in the light/dark box and elevated plus maze." (PMID 39764466, 2024). "Emx1-Cre;Irsp53fl/fl mice displayed hyperactivity in the OFT but normal anxiety-like behavior in the EPM test." (PMID 32116566, 2020). "Because hyperactivity and anxiety are observed in ASD, PMS and schizophrenia, we also evaluated locomotor activities of Emx1-Cre;Shank3Δ14–16 mice." (PMID 31649512, 2019). "The time spent in the center of the arena was not different between genotypes, suggesting that the Emx1-Scrib−/− mutant mice has comparable anxiety level to control littermates (t test: t17 = 0.4595, n.s)." (PMID 33907211, 2021). "IRSp53 deletion in excitatory neurons driven by Emx1 leads to strong social deficits and hyperactivity without affecting anxiety-like behavior, whereas IRSp53 deletion in inhibitory neurons driven by Viaat has minimal impacts on these behaviors in male mice." (PMID 32116566, 2020). "Anxiety-like behavior was further examined in elevated plus-maze, where Emx1-Scrib−/− and control mice showed comparable performance, confirming that Emx1-Scrib−/− mice have no anxiety-related behaviors (t test: t17 = 1.741, n.s)." (PMID 33907211, 2021). "Consistent with a pro-anxiety role, mice lacking 5-HT2A receptors display reduced anxiety that is reversed by Emx1-driven cortical re-expression of 5-HT2A receptors." (PMID 24936175, 2014).
microcephaly (12 papers, 2017 to 2025). A congenital or acquired developmental disorder in which the circumference of the head is smaller than normal for the person's age and sex. "Prmt5F/F; Emx1-Cre (cKO-Emx1) mice show a distinctive microcephaly phenotype, with partial loss of the dorsal medial cerebral cortex and complete loss of the corpus callosum and hippocampus." (PMID 38459149, 2024). "While Scrib loss in Emx1-Scrib−/− mutant mice displays major microcephaly and complete CC agenesis, Nex-Scrib−/− mutant mice display “only” cortical layering defects and partial CC dysgenesis." (PMID 35692812, 2022). "Notably, heterozygous ablation of Hif1α using Emx1-Cre driver causes precocious neurogenic differentiation of neural progenitor cells, resulting in mild microcephaly." (PMID 35361248, 2022). "In contrast, Emx1-Cre;Ddx3xT532M lox/Y conditional hemizygous (cHemi) males exhibit microcephaly and apoptosis." (PMID 41312597, 2025). "Successful microcephaly modeling has been shown in Emx1-Cre-mediated genetic ablation, which nearly completely depletes BubR1 in cortical progenitors and recapitulates microcephaly phenotypes observed in humans." (PMID 37900274, 2023). "Conditional knockout of Ddx3x in neural progenitors using Emx1-Cre leads to microcephaly in female mice." (PMID 35762573, 2022). "Earlier Knl1 deletion by Emx1-Cre led to microcephaly more severe than hGFAP-Cre and a loss of both deep and upper layer neurons." (PMID 31197172, 2019). "Of note, this lethality is not due to microcephaly, as cortical loss across diverse Emx1-Cre models does not reduce viability." (PMID 41312597, 2025). "Like Emx1-Scrib−/− mice, Emx1-Vangl2−/− display partial hippocampal and CC agenesis (but no microcephaly) that is caused by abnormal axonal outgrowth." (PMID 33907211, 2021). "Given that mosaic Cdkn1c-MADM-7 mice (all cells are Cdkn1cflox/+) with heterozygous Cdkn1c deletion in Emx1+ lineage show microcephaly similar like cKO-Cdkn1c-MADM-7 mice, we conclude that the growth-promoting function of Cdkn1c is also highly dosage sensitive." (PMID 31924768, 2020). "Notably, none of the Nex-Scrib−/− cKO mice suffered from microcephaly, and this was expected considering that the main characteristic of this cKO line is to bypass the negative impact of Scrib loss on proliferation and neurogenesis observed in the Emx1-Scrib−/− mutant mice." (PMID 35692812, 2022).
schizophrenia (7 papers, 2017 to 2024). A major psychotic disorder characterized by abnormalities in the perception or expression of reality. "Independent genome-wide association studies showed that single-nucleotide polymorphisms (SNPs) in Emx1, the marker gene of dorsal origin, are associated with schizophrenia, whereas the marker gene of ventral origin lacks any disease association." (PMID 38849524, 2024). "Similarly to MEF2C, the area containing the gene for EMX1 is itself a candidate schizophrenia risk locus." (PMID 36070311, 2022). "Given the well-known association between SHANK3 and various neurodevelopmental disorders, including ASD, PMS and schizophrenia, we first subjected Emx1-Cre; Shank3Δ14–16 mice to behavioral tests in the social domain." (PMID 31649512, 2019). "Our additional analysis revealed that the partitioned schizophrenia polygenic risk score restricted to EMX1 was negatively associated with the P300 amplitude at the nominal P-value threshold." (PMID 37582581, 2023). "These behavioral effects, also seen in global GLS1 HETs with a schizophrenia resilience phenotype, were not seen in mice with an Emx1-driven forebrain reduction affecting most brain glutamatergic neurons." (PMID 28703706, 2017).
gastric cancer (5 papers, 2016 to 2022). A primary or metastatic malignant neoplasm involving the stomach. "In the study, a gastric mucosal biopsy sample was obtained from 826 patients who had undergone endoscopic resection of a gastric cancer, and DNA methylation levels of three preselected marker genes, EMX1, NKX6-1, and miR-124a-3, were measured." (PMID 26823082, 2016). "Downregulation of EMX1/EMX2 genes has been documented to be correlated with the development of several epithelial‐originated solid tumors, such as gastric cancer, lung cancer, endometrial cancer, and colorectal cancer, and restoration of these genes suppressed cancer progression." (PMID 35849030, 2022). "The opposite effects were also produced when the EMX1/EMX2 genes were silenced, indicating that the Wnt pathway is inactivated in the presence of EMX gene expression, as has been preliminarily demonstrated for EMX2 in other tumors, such as lung and gastric cancer." (PMID 34364391, 2021).
autism (4 papers, 2019 to 2025). Persistent deficits in social interaction and communication and interaction as well as a markedly restricted repertoire of activity and interest as well as repetitive patterns of behavior. "For example, ARX is required for normal telencephalic development and is associated with syndromic autism and other neurodevelopmental disorders, while EMX1 and FOXB1 also play important roles in neural development." (PMID 31893020, 2019). "At day 9, EMX1 expression was significantly higher in control compared with autism neural precursors." (PMID 32826066, 2021). "At this stage, control neural progenitors expressed EMX1 significantly higher than autism neural progenitors." (PMID 32826066, 2021). "At day 21, EMX1 expression in both groups appeared to remain stable, with only minor reduction in control precursors (dCTA = −41 cells/day), as opposed to a minor increase (dCTA = +10 cells/day) in the autism group." (PMID 32826066, 2021). "However, in our research, we found that Triofl/fl;Emx1-Cre mice displayed autism-like behaviors including alteration of social behaviors and increased stereotyped behaviors, indicating that the malformation of the suprapyramidal blade was relevant to the development of ASD." (PMID 38907786, 2025).
colorectal cancer (4 papers, 2021 to 2025). A primary or metastatic malignant neoplasm that affects the colon or rectum. "Conditional knockdown of deleted in colorectal carcinoma (DCC) within EMX1 cells causes a spectrum of callosal phenotypes." (PMID 33871356, 2021). "Elevated expression levels of PAX6, BCL11B, MCOLN2, CUX1 and EMX1 reported in colorectal cancer positively correlate with TRPA1 in other malignancies, with a possible implication in tumorigenesis." (PMID 39770499, 2024).
hepatocellular carcinoma (4 papers, 2023 to 2025). A malignant tumor that arises from hepatocytes. "EMX1 was recognized as a potential clinically available epi-marker in hepatocellular carcinoma (HCC)." (PMID 39199304, 2024). "Subsequently, the analysis identified the transcription factor EMX1, which promotes hepatocellular carcinoma metastasis through the EMX1-EGFR-ERK axis in the F3 tier." (PMID 39764438, 2024). "Similarly, analysis of sequencing data from hepatocellular carcinoma (HCC) patients suggested the pivotal role of gene body hypermethylation-activated EMX1-FL (the full-length protein isoform of EMX1) in promoting tumorigenesis and metastasis through EGFR-ERK signaling pathway." (PMID 40517231, 2025).
lung carcinoma (4 papers, 2019 to 2025). "In the tumors tested to date, the restoration of EMX1/2 expression levels suppresses cell proliferation and the invasive phenotype; it also sensitizes lung cancer cells to treatment, suggesting that EMX1/2 may be tumor suppressor genes." (PMID 34364391, 2021). "EMX1 and EMX2 are homeodomain-containing transcription factors, and the function of EMX2 has been linked to the WNT signaling pathway, which has an important role as a suppressor in lung cancer." (PMID 31467637, 2019).
depression (3 papers, 2021 to 2025). "Secondly, depression-related behaviors were observed in the tail suspension test (TST) and forced swimming test (FST), where Emx1-Cre;Klf7F/F mice showed significantly prolonged immobility times." (PMID 40762575, 2025). "To explore possible effects of increased PTEN in the PFC on depression-like behaviors, we injected Cre-dependent PTEN-overexpressing AAV (AAV2/8-DIO-tdTomato-PTEN) or control virus (AAV2/8-DIO-tdTomato) into the PFC of Emx1-Cre mice." (PMID 33771972, 2021).
cognitive deficits (2 papers, 2022 to 2024). "Genetic enrichment of CIRBP in hippocampal neurons CIRBPTg mice bred with Emx1-Cre mice attenuates hypoxia-induced cognitive deficits and neuronal degeneration." (PMID 38388728, 2024). "As we expected, the Arid1afl/+;Emx1‐Cre mice exhibited normal locomotive activities but severe cognitive impairment." (PMID 36385502, 2022).
epilepsy (2 papers, 2018 to 2022). A brain disorder characterized by episodes of abnormally increased neuronal discharge resulting in transient episodes of sensory or motor neurological dysfunction, or psychic dysfunction. "Emx1-IRES-Cre mice are widely used to dissect critical circuitry underlying neurologic disorders such as epilepsy." (PMID 36192157, 2022).
Kallmann syndrome (2 papers, 2014 to 2017). Kallmann syndrome (KS) is a developmental genetic disorder characterized by the association of congenital hypogonadotropic hypogonadism (CHH) due to gonadotropin-releasing hormone (GnRH) deficiency, and anosmia or hyposmia (with hypoplasia or aplasia of the olfactory bulbs). "WDR11 has been shown to interact with the transcription factor EMX1 leading to impaired development of olfactory neurons within individuals with Kallmann syndrome." (PMID 25140149, 2014). "WDR11 binds and colocalizes with the EMX1 transcription factor in the nucleus, and this interaction must be important for its normal function because this capacity is lost by some, although not all, WDR11 mutations in patients with idiopathic hypogonadotropic hypogonadism and Kallmann syndrome." (PMID 28453858, 2017). "We found that the p.I436V mutation, similar to other nearby amino acid substitutions that have been identified in individuals with idiopathic hypogonadotropic hypogonadism with and without anosmia, disrupted interaction of WDR11 with EMX1." (PMID 28453858, 2017).
RASopathy (2 papers, 2024). Developmental syndromes caused by germline mutations (or in rare cases by somatic mosaicism) in genes that alter the Ras subfamily and mitogen-activated protein kinases that control signal transduction. "As the RASopathy model, we used mice heterozygous for the floxed mutation Ptpn11D61Y or KrasV14l as well as for the Emx1-cre allele and as the control, their littermates homozygous for the Ptpn11 or Kras wild-type allele and heterozygous for the Emx1-cre allele." (PMID 38910965, 2024).